RMI2 (RecQ mediated genome instability 2)
Diseases named in the same sentence as RMI2 in open-access papers (continued):
Sharing a sentence is not in itself a finding about the gene and the disease.
cancer (7 papers, 2016 to 2023). A tumor composed of atypical neoplastic, often pleomorphic cells that invade other tissues. "Since proliferation and EMT were considered the main features of cancer, we explored the associations of RMI2 with markers of proliferation and EMT." (PMID 36533385, 2023). "Some reports have revealed that RMI2 is closely associated with a variety of cancers and is considered to be an oncogene." (PMID 36533385, 2023). "Meanwhile, the univariate COX regression also showed that RMI2 expression was associated with OS in 13 cancers." (PMID 35552266, 2022). "KM analysis revealed that high expression of RMI2 was associated with low OS time in 7 cancers, including ACC, GBM, KIRC, LGG, LIHC, MESO, PAAD." (PMID 35552266, 2022). "Meanwhile, the COX analysis also revealed that RMI2 expression was associated with OS in 13 cancer types." (PMID 35552266, 2022). "Our study found that RMI2 is related to DNA methylation in multiple types of cancer, among which BRCA, STAD, UCEC is associated with four DNA methylation genes (DNMT3L, DNMT3B, DNMT3A, DNMT1)." (PMID 35552266, 2022). "Rmi2 is involved in genome stability and has been reported to be associated with development of multiple types of cancer." (PMID 34440888, 2021). "It will be interesting to determine whether individuals carrying rmif-2/RMI2 mutations accumulate fewer genome rearrangements or translocations and whether this is associated with a lower risk of developing cancer compared with Bloom patients." (PMID 34252074, 2021). "Bloom syndrome is caused by mutations in proteins of the BTR complex (consisting of the Bloom helicase, topoisomerase 3, and the RMI1 and RMI2 scaffolding proteins) and the clinical characteristics are growth deficiency, short stature, skin photosensitivity, and increased cancer predisposition." (PMID 34252074, 2021). "It is too early to tell whether homozygous deletion of RMI2 is associated with elevated risk of cancer in late childhood or adulthood." (PMID 27977684, 2016). "RMI2 expression was only a protective factor in four cancer types (CESC, HNSC, THCA, and UVM) increasing the DSS of patients." (PMID 35552266, 2022). "In this research, comprehensive, analyzed the survival relationship of RMI2 expression in multiple cancer types." (PMID 35552266, 2022). "RMI2 expression and M6A-related genes were studied after demonstrating that more than 8 cancer types (BLCA, ESCA, HNSC, LIHC, LUSC, OV, SARC and UCEC) with a strong correlation with m6A related genes." (PMID 35552266, 2022). "KM survival analysis results revealed that high RMI2 expression was related to low OS time in 7 cancers, including ACC, GBM, KIRP, LGG, LIHC, MESO, and PAAD." (PMID 35552266, 2022). "In the current research, we comprehensively demonstrated, the expression level of RMI2 and its immunological relationship to multiple cancer types." (PMID 35552266, 2022). "In our research RMI2 interacts with cell division cycle-associated protein 3 (CDCA3) and cyclin B2 (CCNB2), which are also related with malignant tumors." (PMID 33083148, 2020). "RMI2 may inhibit or promote the progression of cancer by aggregating and regulating immune infiltrating cells." (PMID 35552266, 2022). "Next, the TIMER was utilized to validate the expression of the RMI2 gene in 33 cancers." (PMID 35552266, 2022). "The abnormal expression of RMI2 is negatively correlated with immune cells and stromal cells in most types of cancer, and it is closely related to B cells, CD4 T cells, CD8 T cells, T cells follicular helper and other TILs and a variety of immune-related genes (ICP, MMRs, m6A)." (PMID 35552266, 2022). "We found that there was an abnormally high expression of RMI2 in 22 cancer types." (PMID 35552266, 2022). "In combination, these results revealed that RMI2 is aberrantly overexpressed up to 22 cancer types." (PMID 35552266, 2022). "In recent years, numerous studies have emerged to reveal the relationship between RMI2 and cancers." (PMID 35552266, 2022).
cancer (continued). "Finally, GSEA analysis revealed that RMI2 was engaged in a variety of signaling pathways in pan-cancers." (PMID 35552266, 2022). "We found that in the seven cancer types (BLCA, GBM, STAD, UCEC, COAD, HNSC, LIHC) the expression of RMI2 was positively correlated with MSI-related genes." (PMID 35552266, 2022). "Our research also found that the expression of RMI2 was mainly negatively related to the scores of the immune score and stromal score of TME, such as ACC, GBM, KIRP, LUSC, UCEC, and other cancer types." (PMID 35552266, 2022). "RMI2 expression was related to TMB in 16 cancer types and MSI in 8 cancer types." (PMID 35552266, 2022).
RMI2 also shares sentences with these, for which no sentence is quoted: pancreatic cancer (2 papers); celiac disease (1); cervical cancer (1); genetic disease (1); infection (1); lung adenocarcinoma (1); lupus nephritis (1); lymphoma (1); rheumatoid arthritis (1); type 1 diabetes mellitus (1); type 2 diabetes (1).